BSG (basigin (Ok blood group))
Diseases named in the same sentence as BSG in open-access papers (continued):
Sharing a sentence is not in itself a finding about the gene and the disease.
cholangiocarcinoma (11 papers, 2014 to 2024). A carcinoma that arises from the intrahepatic biliary tree (intrahepatic cholangiocarcinoma) or from the junction, or adjacent to the junction, of the right and left hepatic ducts (hilar cholangiocarcinoma). "For example, the expression of BSG has been found to change significantly in many tumors, including cholangiocarcinoma, colon adenocarcinoma and rectum adenocarcinoma." (PMID 36769187, 2023).
esophageal cancer (10 papers, 2017 to 2025). A primary or metastatic malignant neoplasm involving the esophagus. "BSG rs11473 polymorphism within miR-483-5p binding site was reported to be associated with increased risk of esophageal cancer in a Chinese population." (PMID 28230811, 2017).
heart failure (10 papers, 2017 to 2025). Inability of the heart to pump blood at an adequate rate to meet tissue metabolic requirements. "Collectively, these data may suggest a crucial role of BSG in heart failure caused by pathological myocardial remodeling." (PMID 28230811, 2017). "In mice model, persistent cardiomyocyte-specific overexpression of BSG increases MMPs levels and promotes cardiac fibrosis, adverse LV remodeling, and heart failure in response to chronic pressure overload and during aging." (PMID 28230811, 2017).
asthma (8 papers, 2018 to 2025). "BSG (also called CD147) is a potential target for asthma treatment therapy." (PMID 38540988, 2024).
triple-negative breast carcinoma (8 papers, 2015 to 2025). An invasive breast carcinoma which is negative for expression of estrogen receptor (ER), progesterone receptor (PR), and human epidermal growth factor receptor 2 (HER2). "BSG/CD147 is a multifunctional membrane protein involved in tumor initiation, progression, and metastasis in various cancers, including laryngeal, gastric, renal, and triple-negative breast cancers." (PMID 40723891, 2025).
acute coronary syndrome (6 papers, 2014 to 2025). Signs and symptoms related to acute ischemia of the myocardium secondary to coronary artery disease. "BSG rs8259 polymorphism was associated with BSG expression and risk of acute coronary syndrome." (PMID 28230811, 2017).
astrocytoma (6 papers, 2013 to 2022). "Analysis of the subcellular distribution of BSG and ApoD in 1321N1 astrocytoma cells reveals that both proteins co-localize only on the cell surface." (PMID 35460054, 2022).
cardiac hypertrophy (6 papers, 2019 to 2025). "Other genes such as BSG (CD147) and HLA-A/C are involved in immune and matrix remodeling, while FLCN has been shown to regulate cardiac hypertrophy via mTORC1 signaling in murine models." (PMID 40832351, 2025).
experimental autoimmune encephalomyelitis (6 papers, 2012 to 2024). An autoimmune demyelinating disease of the central nervous system that is produced experimentally in animals by the injection of homogenized brain or spinal cord in Freund's adjuvant. "BSG levels are also elevated in the plaques of individuals with MS, and BSG blockade has been shown to reduce clinical severity in experimental autoimmune encephalomyelitis models." (PMID 39465429, 2024).
neuroblastoma (5 papers, 2016 to 2024). Neuroblastoma (NB) is the most common solid, extracranial childhood tumor. "The upregulation of genes BSG/CD147, CCDC125, GABRB3, GNB2L1/RACK1, HAPLN4, HEBP2, and HSD17B12 is associated with poor neuroblastoma prognosis and low EFS." (PMID 38398114, 2024). "BSG/CD147 has been detected in neuroblastoma-derived exosomes, suggesting it could be regulating the tumour microenvironment to promote neuroblastoma invasion, angiogenesis and metastasis." (PMID 38398114, 2024). "Furthermore, the critical role of BSG/CD147 for SARS-CoV-2 infection, suggests that drugs used for preventing BSG/CD147 mediated viral entry could be repositioned for neuroblastoma treatment." (PMID 38398114, 2024). "To evaluate whether BSG is a requisite for ApoD binding to cell membranes, we performed in vitro binding assays of hApoD exogenously added to membranes of cells that do not express ApoD, like the neuroblastoma cell line SH-SY5Y." (PMID 35460054, 2022).
sarcoma (5 papers, 2014 to 2022). A usually aggressive malignant neoplasm of the soft tissue or bone. "The expression levels of BSG were also upregulated in most tumor tissues compared with normal tissues but downregulated in colon adenocarcinoma, glioblastoma, kidney renal clear-cell carcinoma, rectal adenocarcinoma, and sarcoma." (PMID 36012604, 2022).
type 2 diabetes mellitus (5 papers, 2019 to 2025). A type of diabetes mellitus that is characterized by insulin resistance or desensitization and increased blood glucose levels. "It was further reported that the interaction of SLC16A11 with BSG was dysregulated in Type 2 diabetes variants." (PMID 40355756, 2025).
Arthritis (4 papers, 2012 to 2020). Inflammation of a joint. "Basigin (also known as BSG, CD147, or Extracellular Matrix Metalloproteinase inducer [EMMPRIN]) is a single pass type 1 transmembrane protein that plays a crucial part in developmental processes, wound healing, nutrient transport, inflammation, arthritis, and microbial pathologies." (PMID 32891152, 2020).
Chronic colitis (4 papers, 2023 to 2025). A chronic inflammatory disease of the large intestine (colon, cecum and rectum). "Moreover, a specific inhibitor (AC-73) has been demonstrated to activate autophagy by targeting BSG/CD147 and alleviate chronic colitis-associated intestinal fibrosis induced by trinitrobenzenesulfonic acid." (PMID 38365674, 2024).
gallbladder carcinoma (4 papers, 2015 to 2025). "Another study also found that doxycycline inhibited the proliferation of gallbladder cancer cells by downregulating the expression levels of BSG and induced an early apoptosis response in cancer cells." (PMID 32891152, 2020).
kidney cancer (4 papers, 2013 to 2025). Primary or metastatic malignant neoplasm involving the kidney. "The increasing BSG protein levels were also observed in kidney cancer (for KICH and KIRP), LIHC, THCA, and UCEC." (PMID 35646943, 2022). "In these ten kinds of cancers, compared to corresponding normal tissues, upregulated BSG protein levels were detected in kidney cancer (for KICH and KIRP), LIHC, THCA, and UCEC, consistent with the results at mRNA level (p < 0.05)." (PMID 35646943, 2022). "Indeed, we also validated elevated BSG protein levels in kidney cancer (for KICH and KIRP), LIHC, THCA, and UCEC." (PMID 35646943, 2022).
cardiomyopathy (3 papers, 2017 to 2021). A disease of the heart muscle or myocardium proper. "BSG also exhibited high expression in LV of patients with cardiomyopathy." (PMID 28230811, 2017).
Hepatic steatosis (3 papers, 2020 to 2026). Steatosis is a term used to denote lipid accumulation within hepatocytes. "In the present study, we found that BSG inhibition had the potential to ameliorate insulin resistance and hepatic steatosis." (PMID 34676828, 2021).
lung squamous cell carcinoma (3 papers, 2022 to 2024). "In contrast, in lung squamous cell carcinoma, the expression of PPIA further increased at cancer stage 4, whereas the expression of BSG was similar at all cancer stages." (PMID 36012604, 2022).
influenza (2 papers, 2021 to 2025). An acute viral infection of the respiratory tract, occurring in isolated cases, in epidemics, or in pandemics; it is caused by serologically different strains of viruses (influenzaviruses) designated A, B, and C, has a 3-day incubation period, and usually lasts for 3 to 10 days. "For human/SARS-CoV-2 interactome genes ACE2, TMPRSS2 and BSG, there is a convincing evidence of association in Asians with influenza-induced SARS for TMPRSS2-rs2070788, tag-SNP of the eQTL rs383510." (PMID 34436507, 2021).
invasive breast carcinoma (2 papers, 2014 to 2022). A carcinoma that infiltrates the breast parenchyma. "BSG expression was related to the prognosis of eight cancers (e.g., invasive breast carcinoma) (p < 0.05)." (PMID 35646943, 2022).
measles (2 papers, 2020 to 2023). A highly contagious viral infection caused by the measles virus. "EFNB2 is a receptor for Hendra and Nipah virus, CD4 for human immunodeficiency virus, CXADR is the coxsackievirus and adenovirus receptor, and BSG has been shown to be involved in infection of measles and human cytomegalovirus." (PMID 38140653, 2023). "CD147 (BSG) has been recently shown to act as a receptor for SARS-CoV-2 in cell lines of epithelial origin, which is also a putative receptor for SARS-CoV-2, HIV-1, and measles for entry to host cells." (PMID 33537060, 2020).
medulloblastoma (2 papers, 2022 to 2023). A malignant, invasive embryonal neoplasm arising from the cerebellum. "In group four, medulloblastoma cells’ knockdown of BSG or MMP-2 at the genetic level resulted in a reduction of the ability of cells to invade a collagen-IV–laminin matrix." (PMID 37174066, 2023). "In support of this, stable genetic knockdown of the genes encoding MMP-2 and EMMPRIN (namely MMP-2 or BSG) antagonised the promigratory function of exosomes, confirming that MMP-2 and EMMPRIN are promigratory factors on medulloblastoma exosomes." (PMID 37174066, 2023). "Moreover, BSG gene expression was assessed across a panel of subgrouped medulloblastoma cell lines with known metastatic status." (PMID 37174066, 2023). "Since EMMPRIN is known to induce MMP-2 production and secretion, it was slightly surprising that an increase in MMP-2 function was observed when primary medulloblastoma cell lines were preconditioned with exosomes isolated from BSG knockdown cell lines, (Figure 5Fii)." (PMID 37174066, 2023). "Those with higher BSG expression had significantly worse five- and ten-year overall survival than patients with lower BSG expression, suggesting that the expression level of BSG may represent a negative prognostic factor for overall survival in medulloblastoma patients." (PMID 37174066, 2023).
myopia (2 papers, 2022). "BSG mutation has been implicated in early-onset high myopia and predisposed typical myopic phenotypes in human and mutant mice through a trio-based exonic screening study." (PMID 35153787, 2022). "Nevertheless, a trio-based study of early-onset high myopia using next-generation sequencing and whole-exome sequencing (WES) suggested that de novo mutations of the BSG gene may play a causative role in myopia and may therefore serve as genetic predictors." (PMID 35327754, 2022).
parasitemia (2 papers, 2019). "The differences in median parasitemia between control and anti-BSG antibody treatments were significant (p<0.01)." (PMID 31185066, 2019). "An invasion assay in which unmodified and BSG KO BEL-A-derived reticulocytes were incubated with schizonts at high multiplicity of infection resulted in ~ 60% parasitemia in unedited cells, with no rings observed in BSG KO reticulocytes, confirming the phenotype even under extreme invasive pressure." (PMID 31444345, 2019).
renal dysfunction (2 papers, 2014 to 2024). "Of note, most patients infected with SARS-CoV-2 also suffer from renal dysfunction, which may be due to the high expression of BSG in the kidney and urinary system." (PMID 38484369, 2024).
anaplastic carcinoma (1 paper, 2020). "More interestingly, they also observed MMP-2-positive expression in tumor cells and/or the adjacent tissue in all anaplastic carcinoma (ATC) cases, and the cytological atypia of cells with BSG positive expression was greater than that in cells with negative BSG expression." (PMID 32891152, 2020).
nodular goiter (1 paper, 2020). Goiter characterized by discrete tissue mass(es) that may or may not produce thyroid hormones. "They suggested that cytoplasmic BSG expression levels were significantly higher in TC tissues than in nodular goiter tissues and significantly higher across different pathological stages, and that they closely correlated with lymph node metastasis and depth of tumor invasion." (PMID 32891152, 2020).
non-alcoholic fatty liver disease (1 paper, 2024). "From the KEGG pathway enrichment analysis, the co-expressed genes of BSG enriched in oxidative phosphorylation and non-alcoholic fatty liver disease." (PMID 38484369, 2024).
Pleural effusion (1 paper, 2022). The presence of an excessive amount of fluid in the pleural cavity. "For comparison with other body fluids (i.e., plasma/serum, BAL, and pleural effusion), 153 out of 912 MV proteins were pleural effusion-specific proteins, including ABI1, BSG, CAV1, GRB2, RAS proteins, and SRC." (PMID 35158999, 2022).
scleroderma (1 paper, 2021). Scleroderma is a rare autoimmune connective tissue disorder characterized by abnormal hardening of the skin and, sometimes, other organs. "We note 38 of the genes found expressed in T cells TADs encompassing the scleroderma associated SNPs were also found to be differentially expressed in Dolcino’s study, including BSG, FCER2, GPA33, MAP2K7, SCAMP2, and TSPAN33." (PMID 33894768, 2021).
staphylococcus aureus infection (1 paper, 2020). An infectious process in which the bacteria Staphylococcus aureus is present.
testis cancer (1 paper, 2024). "At protein expression level, BSG was also the highest in testis cancer, which was consist with mRNA expression level." (PMID 38484369, 2024). "The highest level of BSG mRNA was detected in testis cancer." (PMID 38484369, 2024).
thyroid medullary carcinoma (1 paper, 2020). "In addition, researchers have also found that BSG gene silencing leads to growth inhibition of thyroid medullary carcinoma TT cells and alteration of the cell cycle." (PMID 32891152, 2020).
tumor (527 papers, 2001 to 2026). "A coculture model of PAAD cells and pancreatic stellate cells revealed that Gal-3 mediated the Ca2+/−calcineurin–NFAT pathway to increase the transcription of CCL2 and BSG in tumor-associated fibroblasts." (PMID 40600063, 2025). "Patients with higher BSG levels tend to have shorter overall survival and a higher risk of tumor recurrence after surgery." (PMID 38975467, 2024). "We found BSG was expressed in normal tissues and significantly elevated in certain tumor types, suggesting cancer patients are more susceptible to SARS-CoV-2 infection and more likely to develop severe symptoms." (PMID 38484369, 2024). "We observed a significant association between PPIA/BSG overexpression and poor prognosis, such as a low survival rate and high cancer stage, in several tumor types." (PMID 36012604, 2022). "Accumulating studies have found that BSG was over-expressed in many different human tumor cell types, such as those caused by brain cancer, colon cancer, cervical cancer, and endometrial cancer." (PMID 32891152, 2020). "BSG is associated with tumour invasiveness, metastasis, drug resistance and glycolysis and activates multiple pathways including NFkB and JNK which stimulate matrix metalo-proteinases (MMP)." (PMID 24728830, 2014). "The BSG expression was associated with DNA methyltransferases, mismatch repair genes, immune infiltration levels, tumor mutational burden, microsatellite instability, neoantigen, and immune checkpoints, suggesting the potential of BSG as an exciting target for cancer treatment." (PMID 35646943, 2022). "Besides, we performed a similar analysis, finding that BSG exhibited a higher level in HCC specimens than in non-tumor tissues and its diagnostic value was also confirmed." (PMID 33654226, 2022). "BSG was first named “EMMPRIN” for Extracellular Matrix MetalloPRotease INducer, because it was reported to be associated with increased matrix metalloproteases (MMPs) through which it promoted tumour invasiveness and metastasis." (PMID 26099350, 2016). "We further analyzed BSG isoform profile and found that the expression level of BSG-003 isoform containing an Ig_3 domain reached the highest level across pan-cancers, suggesting it may be linked with tumor progression and SARS-CoV-2 infection." (PMID 38484369, 2024). "Module Hep-M20 exhibited the strongest correlation with tumor stage and identified BSG/CD147 as a central hub gene with monotonic upregulation along pseudotime and strong correlation with stemness potential." (PMID 41646335, 2026). "CellChat analysis uncovered a cyclophilin (PPIA/PPIB)-dependent tumor-stroma signaling axis that positions BSG/CD147 as the key mediator for intercellular communication between tumor hepatocytes, fibroblasts and T cells." (PMID 41646335, 2026). "The cell adhesion molecule binding cluster in TuNEPs contained tumorigenic proteins such as ITGA2, CD151, CD9, SLC3A2, and BSG, all known to have an impact on the tumor microenvironment." (PMID 40751052, 2025). "Immunohistochemical analysis revealed a reciprocal expression of TMPRSS11B and BSG together with SLC16A1 in some areas of tumor tissues from PDAC patients." (PMID 40508207, 2025). "An analysis of the positive correlation between BSG and Gal-3 from the TCGA database revealed that the administration of AC-73 (a specific inhibitor of BSG) and gemcitabine markedly diminished the formation of tumor spheres upon rGal-3 stimulation." (PMID 40600063, 2025). "Together these data suggest that TuNEPs induce enhanced outgrowth of tumor cells through adhesion proteins BSG and ITGA2." (PMID 40751052, 2025). "Of note, BSG, expressed by tumor cells, induces the expression of MMPs in fibroblasts or other non-malignant stromal cells through direct or indirect cellular interactions." (PMID 38892056, 2024). "In the TCGA dataset, the expression levels of AKR1B10, ARL6IP4, ATP6V0B, and BSG were significantly up-regulated in the tumor samples." (PMID 38913193, 2024).